IL13RA2 (interleukin 13 receptor subunit alpha 2)
Diseases named in the same sentence as IL13RA2 in open-access papers (continued):
Sharing a sentence is not in itself a finding about the gene and the disease.
breast carcinoma (43 papers, 2010 to 2025). "Of note, Márquez-Ortiz described an ephrin-dependent (EFNB1/EPHB1) mechanism underlying an IL13RA2 function in breast cancer brain metastasis." (PMID 40663259, 2025). "IL13Rα2 has recently emerged as an important driver for metastatic dissemination of breast cancer cells to the lungs and was also associated with reduced metastasis-free survival of breast cancer patients." (PMID 30805303, 2019). "Increased IL13Rα2 levels were also associated with poor metastasis-free survival of patients with breast cancer." (PMID 26208975, 2015). "Interestingly, MDH2 overexpression upregulated several genes associated with breast cancer metastasis (IL13RA2, MMP3, PTGS1, SYK, VCAN, and FLT1) and downregulated several genes associated with metastasis suppression (NOTCH3 and HTRA3)." (PMID 41179294, 2025). "Consistent with our findings, increased immunohistochemical IL-13Rα2 expression was significantly associated with poorer survival outcomes in patients with gastric carcinoma, renal cell carcinoma, colorectal cancers, and luminal-type breast carcinomas." (PMID 39598436, 2024). "Although a previous gene expression profiling study indicated that IL13Rα2 is overexpressed in breast tumors from patients who developed lung metastases, its functional role and underlying mechanism of action in breast cancer development and progression remain largely unknown." (PMID 26208975, 2015). "Further studies in additional patient cohorts will be needed to better delineate the role and prognostic value of IL13RA2 in patients with breast cancer brain metastases." (PMID 40663259, 2025). "Given the overexpression of IL13RA2 in multiple cancer types, and its previous identification as highly expressed in brain-tropic breast cancer cells, we sought to investigate its role in breast cancer brain metastasis." (PMID 40663259, 2025). "Concordantly, elevated IL13RA2 mRNA expression is positively correlated with overall survival in patients with basal-like breast cancer." (PMID 40663259, 2025). "IL13RA2 is highly expressed by brain- and lung-seeking breast cancer cell lines and is often reported to be pro-tumorigenic, pro-metastatic, and correlated with poor patient survival." (PMID 40663259, 2025). "We also examined the link between IL13RA2 expression and initial diagnosis of brain/CNS metastases using data from the Metastatic Breast Cancer project (MBCproject.org)." (PMID 40663259, 2025). "We generated IL13RA2-CRISPR knockout derivatives of the human brain-seeking breast cancer cell line MDA231BrM2, as well as murine 4T1 cells, and evaluated changes in gene expression, proliferation, survival, and metastatic growth in vivo." (PMID 40663259, 2025). "To investigate the role of IL13RA2 in breast cancer metastasis, we generated two IL13RA2 CRISPR knockout models, MDA231BrM2-ΔIL13RA2 and 4T1-ΔIl13ra2." (PMID 40663259, 2025). "Specifically, we observed up-regulation of genes that drive breast cancer metastasis (IL13RA2, MMP3, PTGS1, SYK, VCAN, and FLT1) and downregulation of metastasis-associated suppressor genes (NOTCH3, and HTRA3)." (PMID 41179294, 2025). "In colorectal and breast cancer, IL-13Rα2 stimulated the invasiveness through the Src-PI3K pathway and protein tyrosine phosphatase-1B." (PMID 39598436, 2024). "M3 macrophages secrete chitinase 1-like protein 2 (CHI1L2), which contributes to tumor metastasis through the specific binding to the interleukin (IL)-13 receptor α2 chain (IL-13Rα2) in gastric and breast cancer cell." (PMID 38792805, 2024). "IL13RA2 overexpression was related to poor survival of breast cancer brain metastases and promoted migration of thyroid cancer cells." (PMID 39220137, 2024). "For the determination of IL-13Rα2 mRNA expression, real-time RT-PCR was performed on breast cancer cDNA arrays containing multiple samples representative of the diverse breast cancer phenotypes." (PMID 37345109, 2023).
breast carcinoma (continued). "Consistent with its cytolytic activity, Pep-1-Phor21 readily destroyed IL-13Rα2-expressing breast cancer spheroids with HDAC or DNMT inhibition, further enhancing cytolytic activity." (PMID 37345109, 2023). "To sensitize breast cancer cells to subsequent Pep-1-Phor1 treatment, we also examined the epigenetic regulation of IL-13Rα2 expression in breast cancer cells with a specific focus on HDAC and DNMT inhibitor treatments." (PMID 37345109, 2023). "Further, we defined the specific activity of Pep-1-Phor21 against IL-13Rα2-expressing breast cancer cells and -transfected cells." (PMID 37345109, 2023). "Previous studies in the breast had shown that Activin A regulates breast tumor aggressiveness through IL13Ra2 to promote metastatic spread, and that this occurs primarily in basal-like breast cancers." (PMID 35248133, 2022). "Chitinase 3-like protein 1 (CHI3L1), secreted by M2 macrophages, promotes the metastasis of breast cancer cells by binding interleukin-13 receptor α2 chain (IL-13Rα2) on the membranes of cancer cells." (PMID 35443644, 2022). "The chitinase 3-like protein 1 (CHI3L1) secreted by M2 macrophages specifically binds to the interleukin (IL)-13 receptor α2 chain (IL-13Rα2) of gastric and breast cancer cells, which contributes to tumor metastasis." (PMID 35246045, 2022). "In dogs, the upregulation of interleukin-13 receptor subunit alpha-2 genes was observed in macrophages grown as a co-culture with canine mammary cancer cells." (PMID 32344524, 2020). "For example, activin A signaling promotes breast cancer metastasis by regulating IL13Rα2 expression." (PMID 31827640, 2019). "The findings of this study revealed that CHI3L1 specifically bound to the interleukin (IL)-13 receptor α2 chain (IL-13Rα2) of gastric and breast cancer cells, thus promoting cancer metastasis." (PMID 28143526, 2017). "To decipher the molecular basis for how targeting IL13Rα2 suppressed breast cancer metastasis, we examined the phosphorylation status of STAT proteins and found enhanced STAT6 phosphorylation as the major downstream signaling mediator." (PMID 26208975, 2015). "Consistent with the role of TP63 as a suppressor of breast cancer cell migration, the combination of IL13Rα2 depletion concomitant with IL-13 treatment potently suppressed the migratory potential of metastatic MIV cells." (PMID 26208975, 2015). "IL13RA2 expression has previously been established to be upregulated in lung-metastatic breast cancer cells and in brain tumors." (PMID 26042423, 2015). "Overexpression of the IL13RA2 chain in human breast cancer cell line and pancreatic cancer cell line inhibited tumor development in nude mice, probably mediated by IL-13." (PMID 25481245, 2014). "We previously reported that over-expression of the IL-13Rα2 chain in pancreatic and breast cancer cells by stable transfection induces reduced tumorigenicity in athymic nude mice, indicating that the IL-13Rα2 chain is involved in oncogenesis." (PMID 21067607, 2010). "In the present study, we evaluated prophylactic and therapeutic effect of the IL-13Rα2 cDNA vaccination in syngeneic animal models of D5 melanoma, MCA304 sarcoma and 4T1 breast cancer cells expressing IL-13Rα2 to prime the immune system." (PMID 21067607, 2010). "To investigate whether these survival differences seen in our mouse models had clinical relevance, we assessed the relationship between overall survival and IL13RA2 levels in a cohort of patients with basal-like breast cancer (n = 309) using KM Plotter." (PMID 40663259, 2025). "In addition, the extensive stimulation of IL13Rα2 promotes metastases of breast cancer into the brain and into the lungs, but also a metastasis of CRC into the liver." (PMID 39000142, 2024). "This study addresses the hypothesis that IL-13Rα2 is a druggable target for the treatment of breast cancer." (PMID 37345109, 2023).
breast carcinoma (continued). "Therefore, IL-13Rα2 expression in breast cancer spheroids is selectively amenable to epigenetic upregulation and Pep-1-Phor21 rapidly disrupts spheroid integrity, efficiently killing multiple layers of IL-13Rα2-positive tumor cells." (PMID 37345109, 2023). "Whether these specific signaling events also account for the variable expression of IL-13Rα2 in the various sub-types of breast cancer requires further study." (PMID 37345109, 2023). "Furthermore, IL-13Rα2 expression is regulated via epigenetic mechanisms and, concerning breast cancer, epigenetic activity, including DNA methylation and histone modifications, has been linked to disease progression." (PMID 37345109, 2023). "Whether hypoxia within the breast cancer spheroids accounts for the moderate reduction in IL-13Rα2 expression requires further investigation." (PMID 37345109, 2023). "Therefore, IL-13Rα2 expression is similar in breast cancer tissue samples and representative cell lines with an expression more prominent in TNBC-type tumor cells." (PMID 37345109, 2023). "Notably, IL-13Rα2 expression was found to be epigenetically regulated in breast cancer cells in that the inhibition of histone deacetylase (HDAC) or DNA methyltransferase (DNMT) upregulated IL-13Rα2 expression, thereby sensitizing them to Pep-1-Phor21." (PMID 37345109, 2023). "Our results showed that the expression of IL13Rα2 in MII cells is increased in response to Activin A treatment in a time-dependent manner, suggesting that Activin A could induce IL13Rα2 expression in breast cancer cells." (PMID 30805303, 2019). "Since depletion of IL13Rα2 was previously shown to inhibit migration of metastatic breast cancer cells, we hypothesized that inhibition of Activin A signaling could have a similar effect on MIV cells." (PMID 30805303, 2019). "Subsequent gene expression profiling of metastatic breast cancer cells proficient or deficient in IL13Rα2, and treated with or without IL-13, identified a subset of genes regulated by the IL-13 signaling pathway." (PMID 26208975, 2015). "Similarly, in 4T1 breast carcinoma and D5α2 melanoma models, IL-13Rα2 DNA vaccine boosted with ECDα2 protein showed significant (P < 0.05) antitumor effect compared to the DNA vaccine alone." (PMID 21067607, 2010). "Nevertheless, despite such obstacles, diffuse dead cell staining and spheroid rupture were rapidly detectable post-treatment, indicating that Pep-1-Phor21 could efficiently penetrate breast cancer spheroids, selectively killing IL-13Rα2-expressing tumor cells in the process." (PMID 37345109, 2023). "In human breast cancer tissues, overexpression of interleukin-13 receptor subunit alpha-2 precursor has been suggested as an independent predictor of poorer outcome, playing important roles in cancer cell survival and progression, although it was dependent on the breast cancer subtype." (PMID 32344524, 2020). "To test this hypothesis, we investigated whether concomitant overexpression of INHBA and IL13Rα2 in breast cancer patients can be a significant prognostic factor by separating patients based on combined high or low expression levels of IL13Rα2 and INHBA in each patient." (PMID 30805303, 2019). "Recently, we have shown that interleukin 13 receptor alpha 2 (IL13Rα2) is a critical gene that is overexpressed in a subset of BLBC primary tumors associated with poor distant metastasis-free survival (DMFS) and can promote extravasation and metastasis of breast cancer cells to the lungs." (PMID 30805303, 2019). "Moreover, the ALK4/ALK5 small molecule inhibitor EW-7197 has been reported to potently suppress breast cancer metastasis to the lungs, suggesting that its effects could be mediated, at least in part, through downregulation of IL13Rα2 expression." (PMID 30805303, 2019).
breast carcinoma (continued). "Because decreased TP63 levels have been associated with enhanced invasion and migration as well as metastatic potential of cancer cells, we hypothesized that, upon IL13Rα2 knockdown, IL-13 signaling suppresses metastasis by impairing the ability of breast cancer cells to migrate." (PMID 26208975, 2015). "Because we found that targeting IL13Rα2 enhances STAT6 phosphorylation by IL-13, we hypothesized that this induction may be implicated in modulating the tumorigenic and metastatic properties of breast cancer cells." (PMID 26208975, 2015). "We have shown in this manuscript that IL-13Rα2 exhibits potential as a therapeutic target, particularly for TNBC types of breast cancer." (PMID 37345109, 2023). "We have shown that IL-13Rα2 exhibits potential as a therapeutic target, particularly for TNBC types of breast cancer." (PMID 37345109, 2023). "Given previous reports that IL-13Rα2 expression can be upregulated in certain cancers via epigenetic mechanisms, we sought to clarify whether IL-13Rα2 expression could be similarly enhanced in breast cancer cells, sensitizing them to Pep-1-Phor21 in the process." (PMID 37345109, 2023). "For instance, Massaque and colleagues identified 18 genes, including IL13Ra2, SPARC, MMP1, and MMP2, which can lead to breast cancer metastasis to the lungs." (PMID 35045088, 2022). "We first looked at IL6 and IL13Rα2, which have previously been reported to be regulated by INHBA in ovarian and breast cancers." (PMID 35248133, 2022). "In breast cancer, INHBA signaling promotes breast cancer metastasis by regulating IL13Rα2 expression." (PMID 31827640, 2019). "Similar to our findings in vitro, other investigators have reported the signaling mediated by IL-13/IL-13Rα2 via AP-1 pathways in GBM and other tumor cell lines such as breast cancer, certain types of lung cancer cell line." (PMID 30572904, 2018). "Here, using unbiased gene expression profiling of a well-described human basal-like breast cancer (BLBC) model system, we identified IL13Rα2 as a potent driver of breast cancer metastasis." (PMID 26208975, 2015). "We investigated the prophylactic effect of the IL-13Rα2 DNA vaccine followed by boost vaccination with ECDα2 protein mixed with adjuvants on naturally expressing IL-13Rα2 MCA304 sarcoma and 4T1 breast carcinoma tumors in C57BL/6 and BALB/c mice, respectively." (PMID 21067607, 2010). "For example, in the case of breast cancer, PTP1B is known to regulate IL13Rα2." (PMID 39000142, 2024). "IL-13Rα2 mRNA expression was found to be significantly higher in breast cancer tissues compared with that in non-malignant breast tissues." (PMID 37345109, 2023). "Furthermore, it was demonstrated that targeting IL13Rα2 depletion suppressed breast tumor growth and IL13Rα2 activated IL13-mediated STAT6-signaling pathway, and knockdown of IL13Rα2 suppressed breast cancer metastasis into the lung." (PMID 33917914, 2021). "Recently, we and others have demonstrated that IL13Rα2 is also overexpressed in a subset of BLBC cell lines and primary tumors and could promote migration, extravasation and metastasis of breast cancer cells to the lungs." (PMID 30805303, 2019). "Here, we demonstrate that INHBA depletion downregulates IL13Rα2 expression in metastatic breast cancer cells, whereas treatment with Activin A in non-metastatic cells increases its expression levels." (PMID 30805303, 2019). "Moreover, targeting the decoy interleukin-13 receptor alpha 2 (IL13Ra2) upregulates the metastasis suppressor TP63 in an IL13-mediated, STAT6-dependent manner and impairs extravasation of basal-like breast cancer cells to the lungs." (PMID 29520340, 2018). "Studies have elucidated that IL-13Rα2 expression and subsequent IL-13Rα2-mediated signaling pathways contribute to tumor proliferation, invasion, metastasis, and cellular survival across a spectrum of human cancers, including GBM, prostate, lung, ovarian, pancreatic, gastric, and breast carcinomas." (PMID 38612592, 2024).
breast carcinoma (continued). "Therefore, TSA or 5-aza-dC can selectively upregulate IL-13Rα2 expression in breast cancer cells (particularly in non-TNBC), increasing their subsequent susceptibility to targeting via Pep-1-Phor21." (PMID 37345109, 2023). "Our data presented here also demonstrate that shRNA-mediated depletion of INHBA in metastatic breast cancer cells led to suppression of IL13Rα2 mRNA and protein levels, whereas treatment of non-metastatic cells with Activin A resulted in upregulation of IL13Rα2 expression." (PMID 30805303, 2019). "Interestingly, IL-13Rα2 but not IL-13Rα1 was reported to be involved in pancreatic and breast cancer metastasis." (PMID 27533463, 2016). "Notably, ER expression can be re-established in breast cancer cells after treatment with histone deacetylase (HDAC) inhibitors, raising the possibility that similar mechanisms may also upregulate IL-13Rα2 expression, consequently sensitizing them to IL-13Rα2-targeting strategies." (PMID 37345109, 2023). "Importantly, targeted depletion of IL13Rα2 resulted in dramatic suppression of lung metastasis formation in vivo that is likely to be attributed, at least in part, to STAT6-dependent induction of tumor protein 63 (TP63) expression and suppression of breast cancer cell migration." (PMID 26208975, 2015). "Unlike our results, they found that IL13RA2 expression promoted proliferation in human TNBC and HER2 + breast cancer cells while downregulation impaired brain metastasis." (PMID 40663259, 2025). "Having validated its selectivity, Pep-1-Phor21 activity was further tested against breast cancer cell lines representative of TNBC and non-TNBC phenotypes and of defined IL-13Rα2 expression." (PMID 37345109, 2023). "To test this, we examined IL-13Rα2 expression in both non-TNBC and TNBC breast cancer using representative cell lines, and tissue cDNA- and micro-arrays." (PMID 37345109, 2023). "Adding CHI3L1 protein to gastric cancer cell (MKN-45 and AGS) and breast cancer cell (MDA-MB-231, MDA-MB-435, and MDA-MB-468) cultures promoted the phosphorylation of ERK and JNK but not Src and AKT, which was abolished by IL-13Rα2 gene silencing in cancer cells." (PMID 28143526, 2017). "Finally, based on this evidence, we hypothesized that if a metastasis suppressing IL-13-STAT6-TP63 signaling axis is activated in the absence of IL13Rα2 then STAT6 and TP63 expression levels may coordinately predict survival of patients with breast cancer." (PMID 26208975, 2015).